STAT3 (signal transducer and activator of transcription 3)
Diseases named in the same sentence as STAT3 in open-access papers (continued):
Sharing a sentence is not in itself a finding about the gene and the disease.
psoriasis (continued). "In addition to STAT3, the significance of PAR-1 and MAPK signaling in psoriasis is well-established with respect to keratinocyte proliferation." (PMID 38903528, 2024). "Although the molecular pathway responses to CP in psoriasis are not well characterised, CP inhibits STAT3 activation and significantly remedy inflammatory and epidermal hypertrophic pathologies in a psoriasis mouse model." (PMID 38785562, 2024). "Moreover, psoriasis is characterized by an epidermal barrier dysfunction, which is promoted by the ERK/STAT3 signaling pathway." (PMID 36980194, 2023). "Fourthly, the signaling molecules involved in HFD- or propionate-induced attenuation of psoriasis-like dermatitis have not been clarified and should comprehensively be analyzed, such as NF-κB, STAT3, mTOR, or TLR7." (PMID 37762500, 2023). "In a mouse model of imiquimod-induced psoriasis-like skin lesions, apigenin decreased erythema, scaling, and Psoriasis Area and Severity Index (PASI) score, and it also inhibited NF-kB activation and the IL-23/STAT3/IL-17A pathway." (PMID 38248322, 2023). "In addition to STAT3, STAT1 can also trigger tumorigenesis in psoriasis patients, together with other genes that participate in the cell cycle events." (PMID 36497125, 2022). "In psoriasis, SIRT1 has been reported as a vital detoxifier of ROS-mediated redox signaling pathways, including MAPK, NF-κB, and STAT3, with downregulation of psoriatic inflammatory cytokines, suppression of keratinocyte hyperproliferation, and inhibition of angiogenesis." (PMID 36242051, 2022). "The indications are that PCs may alleviate psoriasis by blocking PI3K and STAT3-dominated inflammation/OS-related signals and stimulating HO-1 antioxidant signals to reduce inflammation and mitigate OS." (PMID 35720176, 2022). "More than 4500 cases and 10,000 controls were investigated in GWAS, where 7 non-HLA susceptibility loci shared by CD and psoriasis (9p24 near JAK2, 10q22 at ZMIZ1, 11q13 near PRDX5, 16p13 near SOCS1, 19p13 near FUT2, 17q21 at STAT3, 22q11 at YDJC) were found." (PMID 36443384, 2022). "Additionally, etanercept inhibited the activation of JAK/STAT3 signaling pathway and promoted the protein expression of SOCS1 and SOCS3 in psoriasis mice." (PMID 36444619, 2022). "MiR-193b-3p inhibitors significantly promoted the expression of psoriasis-related genes and inflammatory genes, as well as the STAT3 and NF-κB pathways in the presence or absence of M5 treatment." (PMID 34667159, 2021). "In brief, owing to their abilities of scavenging free radicals, LPO and modulating multiple redox signaling pathways, such as NF-κB, JAK/STAT3, Nrf2, p38 MAPK, flavonoids are proposed as a prospective antioxidant and anti-psoriatic agent for psoriasis recovery through arresting OS damage." (PMID 34355664, 2021). "It has been shown that the inhibition of NF-κB and STAT3 in murine psoriasis models using benzo[b]thiophen-2-yl-3-bromo-5-hydroxy-5H-furan-2-one (BTH) and inhibition of STAT3 in psoriasis patients using ochromycinone is able to reduce psoriatic skin inflammation." (PMID 34641358, 2021). "The frequency of phosphorylated STAT3-positive cancers was not elevated in the psoriasis group compared to eczema group." (PMID 34679602, 2021). "Together, these results indicate that glycyrrhizin may improve psoriasis by promoting SIRT1 expression and inhibiting STAT3 expression." (PMID 34044769, 2021). "In this study, we found that glycyrrhizin can attenuate the promotion of p-STAT3 induced by SIRT1, which suggests that glycyrrhizin may be beneficial for improving psoriasis by inhibiting the expression of p-STAT3." (PMID 34044769, 2021). "From the results above, we speculate that ERBB4 could promote the keratinocyte proliferation and inflammatory response through the STAT3 and NF-κB pathways, which might represent a novel role of ERBB4 in psoriasis pathogenesis." (PMID 34667159, 2021).
psoriasis (continued). "A previous study reported that oxidative stress contributes to the pathogenesis of psoriasis, and the activation of SIRT1 inhibits the MAPK, NF-κB, and STAT3 oxidative stress signaling pathways, thereby down-regulating inflammatory factors and inhibiting excessive keratinocyte proliferation." (PMID 34044769, 2021). "Moreover, the following genes were upregulated in CD3+ T cells of psoriasis patients—IL17 (105.2 ± 11.01), STAT3 (6.98 ± 1.96), RORC gene in 15.52 ± 2.18, and FOSL1 (5.79 ± 0.99)." (PMID 34445309, 2021). "The Ki-67, as a cell proliferation marker in psoriasis skin, is regulated by the IL6/STAT3 pathway." (PMID 34445513, 2021). "Mechanically, glycyrrhizin inhibits the expression of STAT3 by reversing the inhibitory effect of IL-17A on SIRT1, which may be a potential mechanism by which glycyrrhizin improves psoriasis." (PMID 34044769, 2021). "Together, these results indicated that glycyrrhizin improved psoriasis by inhibiting the expression of IL-17A and IFN-γ in vivo and suppressed the proliferation of IL-17A-HaCaT cells and the expression of STAT3, p-STAT3, and a-STAT3 by upregulating SIRT1 in vitro." (PMID 34044769, 2021). "The expressed hIL22RA is thought to heterodimerize with endogenous IL10RB (IL10 receptor subunit beta), and this complex senses the presence of IL22, driving expression of output molecules to treat psoriasis, IL4 and IL10, via STAT3 (signal transducer and activator of transcription 3) signaling." (PMID 32185403, 2020). "Concerning Th17-related diseases, the small STAT3 inhibitor STA-21 has been tested on psoriasis patients in a nonrandomized study, and psoriatic lesions in six of the eight patients showed improvement after topical STA-21 treatment for 2 weeks (NCT01047943)." (PMID 32226427, 2020). "Oral administration of genistein in psoriasis patients for 8 weeks impaired the transcription of genes overexpressed in psoriasis, CXCL10, IL-6, STAT3, NFKB1, CCL4 while stimulated the transcription of gene repressed in psoriasis, IL-1RN in peripheral blood cells or lesional skin." (PMID 32751360, 2020). "Studies have shown that STAT3 is continuously highly activated in psoriasis compared to other nonpsoriatic, inflammatory skin disorders displaying epidermal hyperplasia." (PMID 32908937, 2020). "MiR-203 is a key factor in psoriasis since it could regulate SOCS3 and lead to the activation of STAT3, hence controlling the proliferation and differentiation of ESCs in skin development and wound healing through P63 and Zfp281." (PMID 32787903, 2020). "The authors developed a CPP that specifically binds to STAT3 called APTstat3 tagged with 9-arginine CPP and conjugated with discoid-shaped lipid NP ((APTstat3-9R)-DLNP) in order to potentiate transcutaneous delivery against psoriasis." (PMID 30634689, 2019). "Recently, it has been reported that the generation of oxidative stress could promote psoriasis through the MAPK, NF-κB, and STAT3 pathways and that it can be alleviated by inhibition of these three pathways." (PMID 31495284, 2019). "We also revealed that BBR could inhibit imiquimod-induced STAT3 action, CDC6 upregulation and psoriasis-like skin lesions in mice." (PMID 30894513, 2019). "Although the molecular mechanisms involved in the pathogenesis of psoriasis are complex, growing evidence suggests that the activator of transcriptions 1 and 3 (STAT1 and STAT3), and nuclear factor-κB (NF-κB) is pivotal in the transcriptome network involved in the mechanism of psoriasis." (PMID 30894513, 2019). "Salidroside, the activator of SIRT1, may cure psoriasis resistant to oxidative stress damage by inhibiting the MAPK, NF-κB, and STAT3 pathways; however, this property of salidroside needs further research." (PMID 31495284, 2019). "Hence, further investigation is required to validate the effects of salidroside on psoriasis pathophysiology and further verify the effect of SIRT1 on MAPK, NF-κB, and STAT3 pathways in the skin." (PMID 31495284, 2019).
psoriasis (continued). "Moreover, followingstimulation of STAT3 phosphorylation by IL-6/IL-22, the ensuing signaling pathwayleads to overexpression of VEGF during psoriasis." (PMID 29630472, 2018). "We also found that IL-22 increases CD147 transcription in vitro and in vivo and that Stat3 binds directly to the CD147 promoter between positions −854 and −440, suggesting that CD147 expression is up-regulated in patients with psoriasis through Stat3 activation." (PMID 28272440, 2017). "In addition, psoriasis-related cytokines, including IFN-γ, TNF-α, IL-17 and IL-22, induced IFI16 up-regulation in keratinocytes via activation of STAT3 signaling." (PMID 27137868, 2016). "To date, the correlation between HO-1 induction/Stat3 activation and the therapeutic effect on experimental psoriasis has not been reported." (PMID 26893174, 2016). "In vitro results showed that several psoriasis-related cytokines, including IFN-γ, TNF-α, IL-17 and IL-22, could up-regulate IFI16 expression in keratinocytes via activation of STAT3 signaling." (PMID 27137868, 2016). "Although cdODN199 includes FOXM1, ISGF3, IRF1 and NF-κB recognition sites, it does not include a binding site for STAT3, previously validated as an effective dODN target in a psoriasis mouse model." (PMID 25883770, 2015). "Furthermore, in transgenic mice with keratinocytes expressing a constitutively active Stat3, suprabasal CK1 was decreased and replaced by CK6, suggesting an alteration of keratinocyte differentiation, as observed in human psoriasis." (PMID 25010647, 2014). "Our results suggest new hypotheses for interpretation of intergenic hits from psoriasis GWAS studies, and we have identified SNPs predicted to influence binding of AP-1, NF-κB, IRF1, STAT3 and STAT4." (PMID 24885462, 2014). "We identified one PP-decreased DEM with genes biased towards hyper-methylation in psoriasis lesions (i.e., PTEN-28; P = 0.01; FDR = 0.16; GSEA), along with two PP-increased DEMs with genes biased towards hypo-methylation (i.e., STAT3-30 and WNT5A-48; P≤0.023; FDR ≤0.23; GSEA)." (PMID 24260178, 2013). "Therefore, our finding that IL-22 induced K17 expression in HaCaT cells by activating STAT3 and ERK1/2 signaling pathways is consistent with the role that these two pathways play in the pathogenesis of psoriasis." (PMID 22808266, 2012). "The list of the DEG in common in the 4 studies contains many genes known to be upregulated in psoriasis, such as IFNγ-regulated genes STAT-1, STAT-3 and MX1; antimicrobial peptides (beta defensin 4, lipocalin 2, S100A7); and pro-inflammatory proteins such as IL-8, CXCL1, IL-1F9, TNFSF10/TRAIL." (PMID 20422035, 2010). "Moreover, the deletion of Stat3 in keratinocytes but not in T cells reduced psoriasis-like dermatitis, indicating that persistent STAT3 activation in keratinocytes leads to the pathogenesis of psoriasis." (PMID 39833165, 2025). "Cutaneous reactions secondary to STAT3 inhibition were less expected given the Janus kinase (JAK)-STAT pathway and the role of JAK inhibition as an important therapeutic tool in many dermatologic inflammatory conditions, including psoriasis and atopic dermatitis." (PMID 40606688, 2025). "These preliminary docking results suggested that PSVII exhibited a strong binding affinity for the Caspase-1 and STAT3 proteins, indicating that STAT3, Caspase-1, and pyroptosis could be key targets and mechanisms for PSVII’s therapeutic intervention in psoriasis." (PMID 40405066, 2025). "Moreover, IL-12p70 activates STAT4 which is thought not to be involved in the pathogenesis of psoriasis in contrast to STAT3 which acts as a key player in the psoriasis-inducing interleukin-23/interleukin-17 (IL-23/IL-17) axis." (PMID 40868162, 2025). "The active ingredients of the three tea alcoholic extracts could modulate multiple signaling pathways through a variety of target proteins such as TNF-α, IL-17, FLG, Cytokeratin 17, IL-23, STAT3, FLG, IFN-γ, IL-22, etc., and thus attenuate or inhibit psoriasis." (PMID 38542915, 2024).
psoriasis (continued). "Comparing core signaling pathways of psoriasis and non-psoriasis and their downstream cellular dysfunctions, STAT3, CEBPB, NF-κB, and FOXO1 are identified as significant biomarkers of pathogenic mechanism and considered as drug targets for the therapeutic treatment of psoriasis." (PMID 37373186, 2023). "A “STAT3 hyperactivated state” in patients with psoriasis but not in HCs may account for the exerted inhibitory effect of GA and that may also be the case for NF-κB." (PMID 36754913, 2023). "Moreover, specific deletion of STAT3 in keratinocytes rather than in T cells reduced psoriasis-like dermatitis." (PMID 35075118, 2022). "The activation of the α7nAChR by its agonist PNU-282987 significantly inhibited the STAT3 signaling activation induced by IL-6 and IL-22, indicating that PNU-282987 had the potential to inhibit Th17-mediated inflammation in the skin and alleviate the psoriasis symptom." (PMID 35351863, 2022). "In the presence of PCs, nevertheless, the proliferation rate and number of psoriasis-like cells evidently decreased (P<0.01), accompanied with enhanced HO-1 and antioxidants, and lowered OS/inflammatory indicators as well as phosphorylated JAK2/STAT3/PI3/AKT (P<0.01)." (PMID 36178125, 2022). "STAT3 inhibitors, including STA-21, may improve psoriasis by potentiating Tregs." (PMID 34501328, 2021). "Interestingly, reduced expression of vitamin D receptors (VDR) has been associated with psoriasis and a lack of VDR has been shown to activate STAT3 signaling in retinal ganglion cell damage." (PMID 34884681, 2021). "We hypothesize that the expression of IL17, STAT3, FOXP3, and RORC and FOSL1 genes in psoriatic skin is correlated with the level of PPARγ expression, and they belong to the same signaling pathway that regulates the development of psoriasis lesion." (PMID 33133175, 2020). "Moreover, these mice also failed to develop psoriasis-like inflammation suggesting the essential role of STAT3 in the production of inflammatory cytokines and development of psoriatic lesions." (PMID 31710084, 2019). "Finally, we demonstrated that BBR could inhibit imiquimod-induced psoriasis-like skin lesions and upregulation of CDC6 and p-STAT3 in mice." (PMID 30894513, 2019). "However, unlike in cSCC, in which YAP functions through the AKT and ERK pathways, YAP may function through the STAT3, JAK2 and NF-κB pathways in psoriasis." (PMID 30323299, 2018). "It suggested that nor@MSC‐EVs may inhibit STAT3‐mediated Th17 activation, offering a reasonable explanation for the observed reduction in splenomegaly of psoriasis mice and further hint at investigating the immunological modulation mechanism of nor@MSC‐EVs treatment for psoriasis." (PMID 39665264, 2025). "Strikingly, in recent reports, IL-6/IL6R-mediated STAT3 activation in keratinocytes, rather than in immune cells, was responsible for the development of the psoriatic phenotype in a mouse model, highlighting the localized production and activity of IL-6 as being fundamental in psoriasis development." (PMID 38672088, 2024). "Moreover, inhibition of STAT3 phosphorylation by the JAK2 inhibitor WP1066 led to a marked attenuation of skin disease, demonstrating the relevance of this pathway for the development of clinical disease, further demonstrating the overlap in pathogenesis between psoriasis and the current model." (PMID 20300524, 2010). "Lastly, the psoriasis-like cell models, treated with PCs in the absence of LY294002 and ZnPP, showed low expressions of p-PI3K, p-AKT, and p-STAT3 proteins, along with a high expression of HO-1 protein." (PMID 36178125, 2022). "Of these nine regulators, four regulators (STAT3, FOXE1,PITX1,TFD) did not overlap with the top 30 regulators of AD, we consider these four regulators as key regulators for psoriasis." (PMID 35874668, 2022).
psoriasis (continued). "In addition, PPPs significantly suppressed the NF-κB and STAT3 pathways and accentuated the expressions of AQP3 and FLG when compared to mice with IMQ-elicited psoriasis without treatment." (PMID 35153762, 2021). "HaCaT cells represent an immortalized keratinocyte cell line and are considered as not very suitable for psoriasis research, because IL-17A or IFN-γ and TNF-α stimulation did not increase the expression of inflammatory markers (e.g., STAT3) or enhance cell proliferation in these cells." (PMID 33801280, 2021). "Besides, STAT3 transgenic mice and SOCS3 knockout mice (the negative regulator of STAT3) have constitutive activation of STAT3 and both develop murine IL-6-driven psoriasis." (PMID 26136626, 2015).